ERBB2 (erb-b2 receptor tyrosine kinase 2)
Diseases named in the same sentence as ERBB2 in open-access papers (continued):
Sharing a sentence is not in itself a finding about the gene and the disease.
breast cancer (continued). "Therefore, our findings warrant further investigations to reveal the synergistic effects of the statin class of medications with tyrosine kinase inhibitors against ErbB2 in the clinical management of ErbB2-positive breast cancers." (PMID 30786890, 2019). "Notably, over-expression or amplification of ErbB2 tyrosine kinase occurs in up to 20% of human breast cancers, where it is predictive of aggressive disease and poor clinical outcome." (PMID 30816273, 2019). "Now, breast cancer is classified as hormone receptor positive based on the expression of Estrogen Receptor (ER), Progesterone Receptor (PR), and Human Epidermal growth factor Receptor-2 positive (ERBB2/HER2+)." (PMID 31496995, 2019). "However, in ERBB2+ breast cancer, the highly elevated levels of ERBB2 lead to a violation of these physiological constraints and the formation of both ERBB2 homodimers and ligand-independent heterodimers." (PMID 30898150, 2019). "To gain mechanistic insight, we determined the effects of c-Src ablation on steady-state mRNA levels in ErbB2-driven mammary tumors using DNA microarrays, identifying 602 transcripts up-regulated and 785 down-regulated in NIC/c-SrcL/L tumors compared to NIC/c-Src+/+ controls." (PMID 31263101, 2019). "EMP2 mRNA expression might be negatively regulated by breast cancer-related receptors (estrogen receptor, progesterone receptor, and ErbB2), because the expression is relatively high in the triple-negative breast cancer cells." (PMID 31652725, 2019). "Furthermore, silencing or blocking RANK diminished metastatic rate, while RANKL treatment had the opposite effect in ERBB2-induced mammary carcinomas." (PMID 31796128, 2019). "Furthermore, we show that MZF1 regulates lysosome trafficking in ErbB2-positive breast cancer cells." (PMID 29396433, 2018). "ErbB2 is an orphan growth factor receptor that facilitates breast carcinogenesis: ~ 20% of human breast cancers show overexpression or gene amplification of ErbB2, and targeted treatment—e.g., with the functional monoclonal antibody trastuzumab—improves the prognosis." (PMID 29566737, 2018). "Unlike amplification of ERBB2 in breast cancer, SPINK1 overexpression has not been associated with gene amplification or rearrangement." (PMID 29460395, 2018). "Ideally in vitro functional assays need to be adapted to any type of molecular alteration including gene amplifications (known to be driver alterations such as ERBB2 in breast cancer), translocations (such as ALK in lung cancer), and deletions of tumor suppressor genes (such as PTEN)." (PMID 29464843, 2018). "For that aim, SKBR3 ErbB2-positive breast cancer cells stably expressing either GFP (SKBR3-GFP) or GFP-nucleolin (SKBR3-NCL) were injected subcutaneously into female nude mice; once tumors formed (~4 days post injection), tumor volumes were measured every 2 days." (PMID 29352243, 2018). "Nevertheless, the anti-cancer efficacy and clinical application of ganetespib for ErbB2+ breast cancer is largely unknown." (PMID 29717218, 2018). "Besides, it was demonstrated that the ErbB2-ErbB3 heterodimer was responsible for the stimulation of downstream oncogenic signaling in ErbB2+ breast cancer cells." (PMID 29455669, 2018). "Thus, the kinome adaptation in lapatinib-resistant ERBB2-positive breast cancer cells is governed, at least in part, by HSF1-mediated heat shock pathway, providing a novel potential intervention strategy to combat resistance." (PMID 29799521, 2018). "High MMP13 and ETV4 mRNA expression levels were associated with negative ER status (P = 0.00067) and the HR−/ERBB2+ subtype (P = 0.0015), two parameters associated with breast cancer aggressiveness." (PMID 29996935, 2018). "In summary, our data indicate that GroA might prove to be an efficient agent in the treatment of breast cancer, including ErbB2-positive tumors." (PMID 29352243, 2018).
breast cancer (continued). "HER2+ breast cancer is characterized by the overexpression of the HER2 receptor, encoded in the ERBB2 gene located on Chromosome 17: Amplification of the Chr17q12 locus leads to the overexpression of the receptor that can be identified through immunohistochemical and transcriptomic approaches." (PMID 30364267, 2018). "These samples can be derived from patients with ErbB2-positive, locally advanced breast cancer." (PMID 30545388, 2018). "MDA-MB-231 human breast cancer cells correspond to a poorly differentiated triple negative breast cancer (TNBC) cell line that does not express the progesterone or estrogen receptors or the receptor tyrosine-protein kinase erbB-2 (ERBB2/Her2)." (PMID 30544833, 2018). "Chromoanasynthesis involving chromosome 17 can lead to ERBB2 amplifications in HER2+ breast cancer." (PMID 30005627, 2018). "Therefore, we investigated the effects of ganetespib on cell proliferation/viability in BT474 and SKBR3 ErbB2+ breast cancer cell lines using an MTT (3-(4, 5-dimethylthiazol-2-yl)-2,5-diphenyltetrazolium bromide) assay." (PMID 29717218, 2018). "However only one of these five pharmacological targets is currently indicated in the clinical practice guidelines for breast cancer: ErbB2." (PMID 30158869, 2018). "PPARγ was shown to protect ErbB2-positive breast cancer cells from palmitate-induced toxicity." (PMID 29599799, 2018). "To examine the specific effects of ganetespib on ErbB2 protein stability in the ErbB2+ breast cancer cells, we treated BT474 and SKBR3 cells with cycloheximide (CHX; 100 μg/mL), an inhibitor of protein synthesis, alone or CHX + ganetespib (1 μM) for the indicated timepoints." (PMID 29717218, 2018). "To further uncover the mechanism of ganetespib-induced apoptosis in ErbB2+ breast cancer cells, we analyzed the expression and/or activation of key apoptotic markers involved in death receptor- and mitochondria-mediated pathways of cell death, after ganetespib treatment." (PMID 29717218, 2018). "Activation of alternate SEMA3C‐driven RTKs may confer escape mechanisms for acquired resistance to RTK inhibitors such as ErbB2 amplification in breast cancer and MET amplification in colon and lung cancer." (PMID 29348142, 2018). "In particular, ErbB2 is a validated therapeutic target for ErbB2-overexpressing breast cancers." (PMID 29717218, 2018). "For this reason, we assumed that targeting of the ErbB2–nucleolin interaction by anti-cancer drugs could represent a potential novel approach to breast cancer therapy." (PMID 29352243, 2018). "Given the oncogenic function of ErbB2 in acquired tamoxifen resistance, miR-34a expression may be a prognostic target to predict tamoxifen responsiveness in ER+ breast cancer patients." (PMID 30214383, 2018). "Moreover, we performed Irf6 IHC analysis of tumor samples derived from the locally advanced ErbB2-positive breast cancers before and after neoadjuvant trastuzumab-based therapies." (PMID 30545388, 2018). "Importantly, CD24 expression has been positively correlated with ERα and ErbB2 status in breast cancer, and Src is involved in the phosphorylation/activation and intracellular localization of ERα and subsequent DNA synthesis." (PMID 30214383, 2018). "Taken together with the calculated t-erbB2 molecular mass, the expression of t-erbB2s (e.g., p110 isoforms) in HER2-positive breast cancer cells may enhance activation of MAPK signaling, supporting a role of t-erbB2s in drug resistance." (PMID 29872719, 2018). "Remarkably, DFT1 cell lines show significantly greater sensitivity to Afatinib than a panel of ERBB2-amplified human breast cancer cell lines (geometric mean DFT1 IC50: 9.8 nM, geometric mean ERBB2+ Breast cancer cell lines IC50: 314.9 nM; p = 0.000516, Wilcoxon rank-sum test)." (PMID 29634948, 2018). "Moreover, frequent amplification of ERBB2 has been reported in breast cancer tumors with high potential for cell proliferation, cell motility, invasiveness, and distant metastases." (PMID 29743853, 2018).
breast cancer (continued). "Such scenario contrasts with exceptional cases of effectiveness, due to the stringent addiction of cancer cells to a given oncogene, such as BCR-ABL in chronic myeloid leukaemia, ERBB2 in breast cancer, ERBB1 in non-small cell lung cancer, B-RAF in metastatic melanoma." (PMID 30089774, 2018). "For the NCOA4-RET fusion-positive, ER+/ERBB2-amplified breast cancer, one can speculate that the presence of NCOA4-RET contributed to its relative resistance to primary treatment with aromatase inhibitor, trastuzumab, and pertuzumab." (PMID 30446652, 2018). "It is now largely used in the treatment of ErbB2-positive breast cancers." (PMID 29662626, 2018). "Nevertheless, the effects of ganetespib on ErbB2+ breast cancer, and the cellular targets downstream of ganetespib-mediated HSP90 inhibition remain unclear." (PMID 29717218, 2018). "Conversely, we have previously shown that invasion of breast cancer cells expressing high levels of ErbB2 could be inhibited by reducing MZF1 expression with MZF1 siRNA13." (PMID 29396433, 2018). "Moreover, CdGAP is an essential component in the synergistic interaction between TGFβ and ErbB-2 signaling pathways during breast cancer cell migration and invasion, and is a novel E-cadherin transcriptional co-repressor with Zeb2 in breast cancer." (PMID 29545927, 2018). "For example, in ERBB2 (also known as HER2) positive breast cancer, the ERBB2 factor would represent the activation of the ERBB2 pathway while the measured copy number, protein and mRNA expression changes will be modeled as appropriately chosen regression functions of the ERBB2 factor." (PMID 30379847, 2018). "As a comparison, amplifications of the ERBB2 gene (encoding for the HER2 protein) in breast cancer result in increased mRNA expression compared with nonamplified tumours for ERBB2." (PMID 30275357, 2018). "Likewise, treatment failures to EGFR and ERBB2 therapies in HNSCC and breast cancer are associated with frequent acquired resistance." (PMID 29458371, 2018). "Similarly, the ERBB2 oncogene is amplified or overexpressed in ~ 20% of breast cancers and inhibitory ERBB2 antibodies are effective in the treatment of these cancers." (PMID 29458371, 2018). "Indeed, our present in vivo experiments performed on ErbB2-positive breast cancer xenograft mice seemed to corroborate our previous findings in the SKBR3 cancer cell line." (PMID 29352243, 2018). "As such, since lapatinib and ganetespib target ErbB2 via different mechanisms, we proposed that the combinational treatment of lapatinib + ganetespib may have synergistic inhibitory effects on ErbB2+ breast cancer cells." (PMID 29717218, 2018). "ABCA1 expression was shown to be regulated by miR‐96 in breast cancer cell lines and AGTR1 was suggested to be a marker of resistance to neoadjuvant chemotherapy in HER2− breast cancer, whereas it was shown to be a therapeutic target in ER+ and ERBB2− breast cases." (PMID 29675884, 2018). "KDM5B is up-regulated in breast cancer cells overexpressing the ERBB2/HER2 oncogene." (PMID 30080846, 2018). "For instance, the presence of a genetic variation in the non-coding sequence of ERBB2 generating a binding motif for the major inducer of epithelial-to-mesenchymal transition ZEB1 can potentially increase the aggressiveness and tumourigenic potential of HER2-positive breast cancer cells." (PMID 29559730, 2018). "In addition, CdGAP mediates transforming growth factor (TGFβ)- and ErbB2-induced cell motility and invasion of breast cancer cells in a GAP-independent manner." (PMID 29545927, 2018). "Inhibition of ErbB2/HER2 and subsequently reduced ErbB signaling in cancer cells results in cell-mediated cytotoxicity, the major proposed mechanism of trastuzumab’s therapeutic effect for breast cancers with over-expression of this pro-survival pathway." (PMID 29399333, 2018). "ErbB2 overexpression occurs in 20–30% of breast cancers and ovarian cancers." (PMID 30241301, 2018).
breast cancer (continued). "However, studies reporting the cellular responses to ganetespib in ErbB2+ breast cancer cells are limited." (PMID 29717218, 2018). "Similarly, well characterized kinases known for their relevance in breast cancer are observed, such as ERBB2, EPHA1, MET and TGFBR2." (PMID 29643987, 2018). "Modeling of amplification by overexpression of wild-type RET sequence validates that RET overexpression, similar to RET fusions, can lead to aberrant downstream signaling like other RTKs such as ERBB2 amplification in breast cancer or MET amplification in lung cancer." (PMID 30446652, 2018). "One approach to testing whether ErbB2 downregulates Irf6 in human breast cancer is to examine whether therapies based on the use of a therapeutic anti-ErbB2 antibody trastuzumab upregulate Irf6 in patients’ tumors." (PMID 30545388, 2018). "Similarly, the ErbB2-induced invasion of human breast cancer cell spheres in 3-dimensional (3D) Matrigel cultures depends on the increased expression and activity of cathepsin B13." (PMID 29396433, 2018). "Nevertheless, the clinical significance and anti-cancer efficacy of ganetespib on ErbB2+ breast cancer is generally unknown and warrants further investigation." (PMID 29717218, 2018). "Since our findings indicate that ganetespib induces the degradation of ErbB2 in ErbB2+ breast cancer cells, we aimed to determine whether ErbB2-overexpressing cancer cells are more sensitive to ganetespib than ErbB2-negative cells." (PMID 29717218, 2018). "ERBB2 amplification (and the resulting protein overexpression) has been identified as a major oncogenic driver in a subset of breast cancers, and its targeted therapeutic modulation by trastuzumab has become a paradigm for successful precision medicine in oncology." (PMID 30333908, 2018). "Research also found that ErbB2 can negatively regulate the expression of miR-205 in breast cancer." (PMID 30356692, 2018). "Furthermore, combined targeting of nucleolin and ErbB2 in breast cancer cells appears to be beneficial in terms of anti-cancer therapy." (PMID 29352243, 2018). "For example, avian erythroblastosis oncogene B-2 (ErbB-2) signalling activates epithelial-mesenchymal transition-promoting Rho family guanosine triphosphates (GTPases), thus enhancing the metastatic potential of breast cancer in experimental settings." (PMID 29402299, 2018). "Additionally, it has been reported that the ZBTB18 exitron splicing expressed in both ERBB2-positive breast cancer and normal breast tissues, but it has higher percent of spliced in value in tumor compared with normal samples." (PMID 29673323, 2018). "The high ERBB2 RNA expression corroborated with strong IHC HER2 staining, the small duplication around ERBB2, and the pathogenic mutation points to an additional mechanism and possible biomarker for HER2+ breast cancer." (PMID 30005627, 2018). "This suggests that not only ERBB2 may be amplified in a subset of breast cancers but also other candidate TAAs located in vicinity of ERBB2 may be coamplified in the same cells." (PMID 29867922, 2018). "Two decades passed since trastuzumab was used for treatment of ERBB2+ breast cancer." (PMID 30123134, 2018). "Currently, the classification of breast cancer is based mainly on the expression of the estrogen receptor (ER), progesterone receptor (PgR), and the overexpression or amplification of human epidermal growth factor receptor 2 (HER2/c-ErbB2)." (PMID 30347895, 2018). "We, therefore, selected the SKBR3 mammary carcinoma cell line with an extra copy of ligand-independent Erbb-2 (Her2) and high endogenous expression of miR4673 to study potential involvement of miR4673 in induction/suppression of non-encoded resistance mechanisms." (PMID 30341280, 2018). "ErbB2/neu plays a critical role in breast cancer development." (PMID 30402124, 2018).
breast cancer (continued). "It has been demonstrated that this ErbB2-NK cell line can recognize both trastuzumab-resistant ErbB2-positive breast carcinoma cells and trastuzumab-sensitive ErbB2-positive breast carcinoma cells, including those cells with low target antigen expression on their surface." (PMID 30567306, 2018). "In MCF-7 breast cancer cells EGCG inhibited the phosphorylation of ErbB2 and ErbB3 and suppressed the MAPK pathway, while in mammary tumor NF639 and SMF cells EGCG reportedly decreased cell proliferation, phosphorylation of ErbB2/neu and inhibited the NF-κB and MAPK pathways." (PMID 30597838, 2018). "ERBB2 transfection in ATRA-sensitive breast carcinoma cells induced ATRA resistance." (PMID 30384831, 2018). "Overall, these data indicate that miR-125a may counteract proliferation and invasion of breast cancer cells through the downregulation of ERBB2, ERBB3, and/or HuR." (PMID 28445974, 2017). "ErbB-2 overexpression in human breast cancer cells also promotes their metastatic potential." (PMID 28460461, 2017). "Since the miR-1296-5p inhibits cell proliferation of breast cancer cell line, a hypothesis is proposed that miR-1296-5p might evoke the apoptosis of ERBB2-positive breast cancer cells by weakening drug resistance." (PMID 29089858, 2017). "To test whether Mek inhibition promotes degradation of ErbB2 in the lysosomes of detached breast cancer cells we treated detached BT474 cells with selumetinib in the absence and in the presence of a lysosomal inhibitor Bafilomycin A1." (PMID 29285258, 2017). "MTT, cell cycle, clonogenic/CFC, ALDEFLUOR, tumorsphere, and Western blot analyses were used to determine the effects of buformin on cell growth, stem cell populations, stem cell-like properties, and signaling pathways in SKBR3 and BT474 erbB-2-overexpressing breast cancer cell lines." (PMID 28193239, 2017). "In concordance with that finding, the group of M.J. Bissell could clearly demonstrate that the response of ErbB2 overexpressing breast cancer cell lines to trastuzumab, pertuzumab and lapatinib was significantly different in 2D and 3D cultures." (PMID 28417948, 2017). "Our data indicate that Mek inhibition blocks ErbB2 expression in detached breast cancer cells." (PMID 29285258, 2017). "Situations when a change in the breast tumor cell density could take place in breast cancer patients and thus affect ErbB2 levels have been described." (PMID 29285258, 2017). "Alcohol exposure caused a drastic increase in the GFR (ErbB1 or HER1), ErbB2 (HER2), ErbB3 (HER3 CSC population and mammosphere formation in breast cancer cells overexpressing ErbB2, but it has a modest effect on breast cancer cells expressing low levels of ErbB2." (PMID 29156633, 2017). "Similarly, buformin inhibited tumorsphere formation, especially of secondary spheres of 78617, an erbB-2-overexpressing mammary tumor-derived cell line, and BT474 cells, indicating its inhibitory activity on CSC self-renewal." (PMID 28193239, 2017). "Here, we found that miR-1296-5p was decreased in ERBB2-positive breast cancer samples when compared to ERBB2-negative breast cancer samples, suggesting that miR-1296-5p might be a tumor-suppressor gene in ERBB2-positive breast cancer." (PMID 29089858, 2017). "In addition, another approach that has been used is to combine the anti-HER2 antibody trastuzumab with a bispecific MM-11 mAb anti-ErbB2/anti-ErbB3 mAb for the treatment of HER2+ breast cancer (NCT01097460)." (PMID 29312320, 2017). "In this study, we tested whether ERRF plays a role in the development of resistance to ERBB2-targeted therapies in ERBB2-positive breast cancer." (PMID 28415602, 2017). "On the other hand, knockdown of ERRF in two lapatinib-sensitive ERBB2-positive breast cancer cell lines compromised the effect of lapatinib on cell survival in 2-D and 3-D cultures, further indicating a necessary role of ERRF in breast cancer's sensitivity to lapatinib." (PMID 28415602, 2017).